RN7SKP166 (RN7SK pseudogene 166)
Gene: Miscellaneous RNA gene on chromosome 12 (66,292,683 to 66,292,987, forward strand). Ensembl gene ENSG00000222744.
Homologues: Orthologues: chimpanzee 7SK (98% identical). Paralogues in human: 7SK (78% identical), RN7SKP79 (76% identical), RN7SKP133 (75% identical), RN7SKP38 (75% identical), RN7SKP78 (75% identical), RN7SKP187 (74% identical), RN7SKP9 (74% identical), RN7SKP217 (74% identical), RN7SKP185 (73% identical), RN7SKP245 (73% identical), RN7SKP48 (73% identical), RN7SKP77 (73% identical), and 284 more.